IL10 (interleukin 10)
Diseases named in the same sentence as IL10 in open-access papers (continued):
Sharing a sentence is not in itself a finding about the gene and the disease.
Obesity (continued). "In fact, IL10 can attenuate not only mild inflammatory activity in the hypothalamus, as the one associated with obesity, but also more severe inflammatory activity, such as the one induced by LPS." (PMID 28086928, 2017). "Supporting an effect of severe obesity, the association between BMI and IL10 expression was only significantly affected when analyses included the 19 individuals with a BMI ⩾40." (PMID 28244985, 2017). "Diet-induced gerbil obesity model showed decreased levels of adiponectin and IL-10 in adipose tissue, suggesting an association between metabolic disorders found in plasma and liver and the altered levels of these cytokines." (PMID 28265495, 2017). "The A allele of the -1082 polymorphism of the IL-10 gene has been associated with insulin resistance and obesity." (PMID 27555379, 2017). "These cells seem to contribute to supporting inflammation and loss of regulation in immune response in children with obesity, especially by alteration in IL-10 and TGF-β expression." (PMID 27977792, 2016). "A promoter polymorphism (−592C/A) was associated with lower circulating IL-10 levels and an increased risk for obesity and insulin resistance in Italian people." (PMID 23941335, 2013). "In adults, low circulating IL10 has been associated with obesity, cardiovascular disease and type 2 diabetes." (PMID 23941335, 2013). "Our study confirmed that low IL10 concentration is associated with overweight and obesity in young adolescents." (PMID 23941335, 2013). "In adults, low circulating interleukin 10 (IL10) has been associated with obesity and type 2 diabetes." (PMID 23941335, 2013). "report that IL-10 produced by Tregs cause diet-induced obesity." (PMID 40352719, 2025). "At the same time, the authors emphasise that the decrease in IL-10 may also be mediated by the metabolic side effects of antipsychotics, given that obesity and metabolic syndrome are associated with a reduction in anti-inflammatory cytokines, including IL-10." (PMID 41008291, 2025). "Additionally, changes in IL-10 levels are negatively associated with various metabolic disorders, such as high BP, obesity, high HDL and LDL concentrations, dyslipidemia, and glucose intolerance." (PMID 39408048, 2024). "Moreover, IL-10 overexpression increases insulin sensitivity, protects skeletal muscle from obesity-associated macrophage infiltration and decreases production of inflammatory cytokines." (PMID 36994095, 2023). "However, IL-10-expressing CD8+ T cells isolated from the livers of mice with obesity-associated NASH have also the capabilities of promoting hepatic fibrosis by directly stimulating macrophage and HSC activation." (PMID 38077334, 2023). "IL-10 in the serum is positively associated with obesity in humans." (PMID 35250869, 2022). "Perhaps, the association between IL10 and type 2 immunity observed in helminth infections, the modified Th2, may shift the impact of IL10 on obesity." (PMID 35499991, 2022). "We propose that the WAT IL-10 might exert protective effects in obesity-associated chronic inflammation in women which could be one of the contributing factors for the decreased morbidity observed in women during obesity than men." (PMID 36313784, 2022). "However, little is known regarding the relationship between SNPs of the IL10 gene and the risk of overweight and obesity in young men." (PMID 35205336, 2022). "However, little is known regarding the relationship between SNPs of the IL10 gene and the risk of obesity in young men." (PMID 35205336, 2022). "We propose that the scWAT IL-10 might exert protective effects in obesity-associated chronic inflammation but that this mechanism is absent in men." (PMID 36313784, 2022). "Lower levels of plasma IL-10 after bariatric surgery, alongside its close association with IL-1β, suggest that IL-10 might be secreted in obesity as a compensatory anti-inflammatory mechanism." (PMID 34108550, 2021).
Obesity (continued). "IL-10 deficiency aggravates renal inflammation, fibrosis and functional failure in high-fat dieted obese mice, thus IL-10 therapy could be applied to obesity-related chronic renal failure." (PMID 33547567, 2021). "Low IL-10 circulating levels are reported to be associated with obesity and metabolic syndrome." (PMID 34834553, 2021). "Understanding the effect of IL-10 deficiency in obesity could provide new therapeutic opportunity for renal." (PMID 33547567, 2021). "Published literature shows that lotus leaf reduces the levels of inflammatory cytokines IL-1β, TNF-α, IFN-γ, and IL-6, increases the levels of anti-inflammatory cytokines IL-4 and IL-10, and inhibits inflammation caused by high-fat diets accompanied by obesity." (PMID 34992717, 2021). "The excessive accumulation of insulin inhibits the proliferation of Treg cells, thus reducing IL-10 production, and the decreased number of Treg cells in obesity leads to decreased IL-10 secretion; thus, insulin further exacerbates the development of obesity-associated AT inflammation." (PMID 34515616, 2021). "IL-10 can protect against obesity-associated AT inflammation." (PMID 34515616, 2021). "Obesity was related to the enhanced TNF-α and reduction in local IL-10, which mediated the aromatase and estrogen biosynthesis in mammary adipose tissue, providing novel insight for prevention strategy of post-menopausal obesity-associated BC." (PMID 34350120, 2021). "In addition, children with overweight or obesity tend to have lower concentrations of IL-10 and IGFBP-1, which can predispose them to low grade inflammation often reflected in higher circulating levels of CRP and resistin." (PMID 33266497, 2020). "The study further shows that the effects of diet on TNF-α/IL-10 ratios were linked to distinct patterns of NF-κB accumulation in the nucleus: while RelA was the NF-κB subunit most impacted by obesity in adipose tissue macrophages, cRel was the subunit affected in peritoneal macrophages." (PMID 31316525, 2019). "Moreover, Tregs associated with obesity and hyperinsulinemia are deregulated with reduced IL-10 production and increased interferon gamma (IFN-γ) production, exacerbating meta-inflammation." (PMID 31475003, 2019). "Clarifying the role of IL-10 in lipid metabolism may provide a new therapeutic strategies in obesity-association disorders." (PMID 29895283, 2018). "Thus, dysregulation of IL-10 is directly or indirectly associated with pathogenesis of obesity-related hypertriglyceridemia." (PMID 29895283, 2018). "The association of obesity with IL-10 (Interleukin-10) and the inflammasome pathways is very interesting, because previous studies have suggested that molecular perturbation in obese individuals with TNBC may be related to metabolism and inflammation." (PMID 30360534, 2018). "Moreover, reduced NK cell survival and expansion of IL-10-producing NK cells have been described in other obesity-associated cancers." (PMID 30455701, 2018). "Previous studies demonstrated that the stronger butyrate-induced expression of IL-10, a modulator of Treg function, may be crucial for obesity-associated and systemic inflammation." (PMID 28904265, 2017). "Interestingly, this behavior corresponds to the observed increase in Th1 and Th17 and the decrease in Treg cells and IL-10 under obesity-associated chronic inflammation." (PMID 28651594, 2017). "In addition, the low IL-10 production capacity presented in pathological conditions such as obesity is associated with the development of metabolic syndrome and T2D." (PMID 25960614, 2015). "Conversely, insufficient levels of IL-10 may increase the risk for autoimmunity, obesity, and other inflammatory disease syndromes." (PMID 24392159, 2014). "A decline in serum IL10 concentration in overweight and obese adolescents may further contribute to the IL1β-mediated inflammatory environment associated with obesity." (PMID 23941335, 2013).
Obesity (continued). "A decline in IL10 concentration in overweight and obese adolescents may further contribute to the IL1β-mediated inflammatory environment associated with obesity." (PMID 23941335, 2013). "Furthermore, IL-10 treatment prevents muscle insulin resistance by decreasing obesity-associated macrophages and cytokines in muscle from high-fat diet-treated mice." (PMID 24027356, 2013). "Although this review focused on only two of the inflammatory cytokines, many other adipokines and chemokines have been associated with obesity (e.g., adiponectin, IL-1, IL-10, and MCP-1), and are sensitive to dietary fatty acid intake and should be studied further." (PMID 23698162, 2013). "Since obesity is known to reduce expression of proinflammatory cytokines in the spleen, we examined whether spleen-derived IL-10 regulates NAFPD caused by high-fat (HF) diet-induced obesity." (PMID 23285260, 2012). "Interestingly, BM upregulated specific Th2 cytokines IL-5, IL-10 and IL-13, which have been demonstrated to protect obesity-associated inflammation." (PMID 21639917, 2011). "Oscillospira and interleukin (IL)-10 levels have been linked to gut pathophysiology and microbiota alterations in diet-induced obesity, along with intestinal paracellular permeability as potential early dysfunctions in the gut that might lead to metabolic disorders and obesity." (PMID 38332014, 2024). "Interestingly, Treg-specific loss of IL-10 resulted in increased insulin sensitivity and reduced obesity in high-fat diet-fed male mice, suggesting that Tregs may promote healthy obesity in some settings." (PMID 35039633, 2022). "Thus, targeting AT IL-10 could be a potential therapeutic strategy for obesity and its associated metabolic disorders." (PMID 35909571, 2022). "Therefore, reduced IL-10 production stemming from a smaller Treg cell population may exacerbate obesity-associated AT inflammation, suggesting that IL-10 plays an important role in resisting AT inflammation." (PMID 34515616, 2021). "Finally, the influence of IL-10 deficiency in obesity was analyzed for renal function." (PMID 33547567, 2021). "Collectively, this data suggests that independent of gender, aging drives peripheral expansion of immunoregulatory networks including Treg and Tr1-like cells and IL-10 that could actively and cumulatively participate in limiting the severity of obesity-associated metabolic derangements." (PMID 34099626, 2021). "IL-6 signaling is not only required to induce IL-10 expression, but is also involved in T cell differentiation to IL-17-expressing T cells, thereby further complicating the exact definition of cell type specific contributions of inflammatory mediators in obesity and its associated disorders." (PMID 30591653, 2018). "High-dose CU262 in particular brought IL-6/TNF-α down and IL-10 up relative to HFD alone (p < 0.05), indicating an attenuation of obesity-associated systemic inflammation." (PMID 41596930, 2026). "For example, in the adipose tissue, Tregs driving the Blimp-1-mediated production of IL-10 negatively regulate metabolic pathways that drive obesity and insulin resistance." (PMID 40002370, 2025). "The transcription factor Blimp-1 was previously shown to drive the secretion of IL-10 in regulatory T cells (Tregs), thus facilitating obesity and insulin resistance." (PMID 40352719, 2025). "Muscle-derived IL-6 can inhibit the production of inflammatory cytokines such as TNF-α and IL-1β, while promoting secretion of anti-inflammatory cytokines like interleukin-10 (IL-10), thereby improving inflammatory profile in patients with sarcopenic obesity." (PMID 41141350, 2025). "Conversely, adiponectin exerts anti-inflammatory effects by stimulating IL-10 and IL-1RA production, but its levels are typically reduced in obesity." (PMID 41367390, 2025). "In healthy and high-fat diet–induced obesity in rodents, splenectomy increased inflammation and collagen infiltration within the islets due to a response mediated by a reduction in IL-10." (PMID 40276696, 2025).
Obesity (continued). "Taken together, the microenvironment in obesity suppresses NK cells and is probably mediated by IL-10+ Tregs." (PMID 40352719, 2025). "Lactobacillus sakei, Lactobacillus mucosae, and Bifidobacterium adolescentis attenuate gut inflammation, obesity, and hepatic steatosis by producing anti-inflammatory IL-10." (PMID 40696355, 2025). "Anti-inflammatory mediators such as IL-10 play a compensatory role but are usually reduced in individuals with obesity." (PMID 41367390, 2025). "Obesity reduces the level of IL-10 (an anti-inflammatory cytokine), and this, along with overproduction of inflammatory mediators such as tumor necrosis factor-α and IL-6, leads to progression of MASLD." (PMID 40881517, 2025). "Obesity, a major risk factor, is associated with elevated pro-inflammatory markers (TNF-α, IL-6) and reduced anti-inflammatory IL-10 and adiponectin." (PMID 40941639, 2025). "In individuals with obesity or MetS, Breg cells tend to reduce the number of IL-10 secreting cells, increase autoantibody production, and increase the number of TNF-α and IL-6-producing cells." (PMID 40696355, 2025). "White adipose tissue beiging: The role of Blimp-1 in the regulation of IL-10 is important in metabolic diseases such as obesity and insulin resistance." (PMID 40002370, 2025). "Butyrate and propionate inhibit the secretion of reactive oxygen species, nitric oxide, TNFα, and IL-6 while promoting the production of the anti-inflammatory interleukin 10 (IL-10), which is beneficial in obesity." (PMID 40864791, 2025). "Studies have shown that obesity can recruit inflammatory factors such as IL‐17A and IL‐10,11, 12, 13 and promote the production of MDSCs." (PMID 38501542, 2024). "Based upon the cytokine production patterns of splenic T helper cells upon stimulation with PMA, obesity seems to enhance the capacity of these cells to produce IL-10, while it diminished IL-17A production." (PMID 39201761, 2024). "Overweight/obesity was also linked to increased plasma levels of IL-5, IL-17A, IL-22, IL-33, TNF-α, and leptin and decreased levels of IL-10." (PMID 39902293, 2024). "B1a cells are identified as the major producers of B cell-derived IL-10, which exerts anti-inflammatory functions in obesity-induced AT inflammation." (PMID 38455510, 2024). "Cytokines secreted by adipose tissue, such as IL-1β, IL-10, and IL-18, are elevated in both obesity and AD." (PMID 39273520, 2024). "We identify an important network involving Tlr9, Irf4 and Il-10 interconnecting metabolic homeostasis, with the function of B and T cells, and gut microbiota in obesity." (PMID 38762479, 2024). "The levels of IFN-γ, IL-4 and IL-10 in two undernutrition infected groups were higher than those in normal + infection and obesity + infection groups, while the results of TNF-α and IL-12 p70 were not different among the groups." (PMID 38185681, 2024). "IL-10 usually has an anti-inflammatory effect; however, when IL-10 is ablated, mice exhibit anti-obesity traits, including increased energy expenditure and adipose thermogenesis." (PMID 39582861, 2024). "Previous reports on IL-10 are heterogeneous, with reduced levels in subjects with obesity, elevated levels in females with obesity, or elevations associated with visceral fat loss." (PMID 39683518, 2024). "The anti-inflammatory cytokine interleukin (IL)-10 is strongly and negatively associated with muscle strength and is positively related to obesity, and low IL-10 levels are related to MS." (PMID 39408048, 2024). "Cytokine analysis indicated a decrease in pro-inflammatory markers, such as MCP-1, and a significant increase in anti-inflammatory cytokines like IL-10, suggesting potential benefits in reducing obesity-related inflammation." (PMID 39683663, 2024). "Recent animal studies have shown that the genetic deletion of IL-10 exacerbates obesity-induced atrial inflammation, fibrosis, and fibrillation and that IL-10 therapy can inhibit this pathology." (PMID 39742001, 2024).
Obesity (continued). "Human IL-10-modified UC-MSCs also showed successfully alleviated high-fat diet (HFD) that induced the obesity in mice." (PMID 37726805, 2023). "Previous studies also found increased levels of TNF-α and IL-10 in serum or liver tissue in obesity-related NAFLD rat and mouse models established by high-fat diet or monosodium glutamate (MSG) injection." (PMID 37174318, 2023). "Differences between the overweight, obese and severe obesity groups were observed for IL-1β, IL-6, and IL-10." (PMID 37336969, 2023). "Previous studies have shown that IL-10 exerts anti-inflammatory effects in various diseases including traumatic brain injury, stroke, spinal cord injury, and obesity." (PMID 38093354, 2023). "The importance of spleen-derived IL-10 in protection against obesity-related CKD has been demonstrated by the study with IL-10 knockout mice." (PMID 37630806, 2023). "In adolescents with obesity, the decrease in IL-10 and the increase in IL-1β stimulate hepcidin release, while in childhood obesity, the increase in miRNA-122 can limit hepcidin levels." (PMID 38140340, 2023). "IL-10 has been shown to be critical in the control of obesity-induced neuroinflammation, warranting the proper functionality of POMC/AgRP neurons in rodents." (PMID 36829858, 2023). "Consistent with changes in pro-inflammatory cytokines, suppressing interleukin-10 (IL-10) induces thermogenic gene expression, whereas deleting the IL-10 receptor enhances beige fat formation and blunts obesity." (PMID 37020585, 2023). "This phenomenon is consistent with other studies that have reported that IL-10 decreases with age and obesity in animal and human models, especially in obese women." (PMID 37139092, 2023). "Treatment of miR-17–92−/− mice with anti-TNFα suppresses obesity and increases IL-10 via upregulation of Fos Proto-Oncogene expression, suggesting that miR-17–92 controls obesity by upregulating Il10 and suppressing Tnfa." (PMID 36994095, 2023). "IL-10 has also been found to suppress the production of pro-inflammatory cytokines and protect from TNFα-induced insulin resistance in obesity." (PMID 36994095, 2023). "In conclusion, IL-1β, IL6, IL-10, and IP-10 levels are elevated in adolescents with severe obesity and these cytokines can serve as a tool for the diagnosis of MetS." (PMID 37336969, 2023). "Studies have demonstrated significantly lower Adpn and IL-10 concentrations among youth with obesity compared to normal weight, potentially hampering the defense mechanisms against inflammation." (PMID 37299403, 2023). "Decreased levels of the anti-inflammatory IL-10 have been found in obesity, insulin resistance, and dyslipidemia patients." (PMID 37875953, 2023). "As an anti-inflammatory cytokine, IL-10 has been suggested to attenuate AT inflammation and improve insulin sensitivity in conditions of obesity." (PMID 35909571, 2022). "Studies using a rodent model of neuropathic pain and obesity demonstrated that tDCS can prevent increases in IL-1β, TNF-α and IL-10 triggered by chronic constriction injury in a neuropathic pain model or hypercaloric diet in a model for obesity." (PMID 36620466, 2022). "While IL‐10, an anti‐inflammatory cytokine, is usually lower in patients with obesity, TNF‐α, a proinflammatory cytokine, shows the opposite trend." (PMID 35837843, 2022). "The difference between IL10 expression in men and women with obesity and T2D had a borderline significance (p=0.053)." (PMID 36313784, 2022). "Obesity directly drives adipocyte cells towards inflammatory phenotypes, releasing pro-inflammatory cytokines, such as leptin, IL-6, IL-10, TNF-α." (PMID 35069893, 2022). "In contrast, a recent study reported that IL-10 was upregulated in subcutaneous white AT in female patients with obesity and insulin resistance." (PMID 35909571, 2022). "Both animal experiments and epidemiological data have demonstrated that obesity leads to a systemic reduction in IL-10 levels in obese individuals." (PMID 35313972, 2022).